FDX1 (ferredoxin 1)
Diseases named in the same sentence as FDX1 in open-access papers (continued):
Sharing a sentence is not in itself a finding about the gene and the disease.
melanoma (14 papers, 2018 to 2025). A malignant, usually aggressive tumor composed of atypical, neoplastic melanocytes. "Elevated FDX1 expression has been linked to the enhanced effectiveness of PD-L1 blockade immunotherapy in melanoma, as observed in the GSE22155 and GSE172320 cohorts." (PMID 37298135, 2023). "For example, FDX1 has been identified as a positive upstream regulator of cuproptosis, and its expression is decreased in high-risk melanoma, as classified by CRGs; however, its knockdown inhibited melanoma cell proliferation in vitro." (PMID 38336727, 2024). "Taken together, our results suggest that FDX1 is aberrantly expressed in melanoma and may be associated with patient prognosis." (PMID 36341437, 2022). "Interestingly, high FDX1 expression in melanoma is linked to improved response to anti-PD-L1 immunotherapy, but FDX1 knockdown inhibits the in vitro proliferation of melanoma cells." (PMID 41170386, 2025). "Recently, several in vitro experiments have demonstrated that FDX1 promotes the growth and migration of melanoma cells." (PMID 38515849, 2024). "The results of TIDE analysis showed that FDX1 expression was correlated with the response to PD1 immunotherapy in a cohort of patients with melanoma and kidney tumors." (PMID 36226187, 2022). "FDX1 is highly expressed in human malignant melanoma cells, which correlates with resistance to apoptosis induced by ultraviolet treatment." (PMID 36210836, 2022). "Melanoma is more likely to occur in individuals who express high levels of FDX1; hence, this gene could serve as a prognostic marker for patients with melanoma." (PMID 38515849, 2024). "The results showed that melanoma patients with higher FDX1 expression might present with different efficacy of PD-L1 immune response during diverse immunotherapy stages." (PMID 37298135, 2023). "For example, high FDX1 expression in cancer stem cells decreased proliferation and overturned the epithelial–mesenchymal transition via tumor resistance to ammonified in human melanoma and promoted the treatment of resistant acute myeloid leukemia." (PMID 37298135, 2023). "Furthermore, our in vitro experiments showed that FDX1 promoted the growth, and migration of melanoma cells." (PMID 36341437, 2022). "Survival analysis in the literature showed that the higher the level of FDX1 mRNA, the better the anti-PD-1 treatment effect in not only KIRC but also melanoma." (PMID 39206152, 2024). "We found that the expression of FDX1, LIAS, LIPT1, DLD, DLAT, MTF1, and CDKN2A were significantly lower in melanoma than in normal tissues." (PMID 36824136, 2023). "A key player is ferredoxin 1 (FDX1), which is highly expressed in melanoma and other cancers." (PMID 41170386, 2025). "Furthermore, in vitro experiments were conducted to validate the relationship between FDX1 expression and PD-L1 expression in SKCM cancer using melanoma cells from WM115 and A375." (PMID 37298135, 2023). "More importantly, the immunotherapy data suggested that FDX1 can serve as a potential predictor for the assessment of immunotherapy efficacy in KIRC, with higher FDX1 expression levels leading to better immunotherapy efficacy, which was confirmed in two other melanoma cohorts." (PMID 39206152, 2024). "Moreover, we detected that PD-L1 expression was positively correlated with some cuproptosis-related genes (CDKN2A, FDX1, LIPT1, and MTF1), but negatively correlated with other cuproptosis-related genes (ATP7B, DLST, and PDHA1) in an analysis of 470 melanoma patients." (PMID 35837286, 2022). "On the other hand CYT-low metastatic melanomas had recurrent amplifications in loci 5p15.33 (TERT), 6p25.1 (CDYL), 7p22.2 (RAC1), 12q15 (MDM1) and recurrent deletions in 5q31.2 (CTNNA1, FGF1), 11q22.3 (FDX1, RDX, ZC3H12C), and 15q14 (RASGRP1, CSNK1A1P1, SPRED1)." (PMID 33779796, 2021). "Therefore, we speculate that FDX1, as a CRG, is a marker of melanoma." (PMID 36341437, 2022).
glioblastoma (13 papers, 2022 to 2025). The most malignant astrocytic tumor (WHO grade IV). "Our investigation has revealed a positive correlation between elevated FDX1 expression in glioblastoma multiforme (GBM) patients, increased levels of tumor-associated macrophages, and reduced expression of CD4 + and CD8 + T cells, aligning with previous findings." (PMID 38114959, 2023). "In this study, we demonstrated that in human glioblastoma-derived cell lines, T98G and A172, under severe hypoxia (with oxygen concentrations below 0.1%), FDX1 regulates the activation of key radioresistance factors, including ATM, DNA-PKcs, Akt, and EGFR." (PMID 40244269, 2025). "We first examined the effects of severe hypoxia on the expression of FDX1 in human glioblastoma cell lines." (PMID 40244269, 2025). "In this study, we examined the role of FDX1 in regulating cellular responses to severe hypoxia in glioblastoma cell lines T98G and A172." (PMID 40244269, 2025). "The results show that FDX1 was lowly expressed in most cancers but higher in glioblastoma multiforme, stomach adenocarcinoma, and uterine corpus endometrial carcinoma." (PMID 36210836, 2022). "In this study, we aimed to determine whether FDX1 contributes to radioresistance in human glioblastoma cells under severe hypoxia and whether it regulates key factors such as ATM, DNA-PKcs, Akt, and EGFR, which are highly expressed in cancer cells." (PMID 40244269, 2025). "Consequently, we conducted a comprehensive examination of the impact of FDX1 on various aspects of glioblastoma multiforme's (GBM) tumor microenvironment (TME), metabolic pathways, immune micro-environment, and drug responsiveness." (PMID 38114959, 2023). "The differential expression analysis result demonstrated that the FDX1 was highly expressed in tumor tissues than in normal tissues in glioblastoma multiforme (GBM), brain lower-grade glioma (LGG), stomach adenocarcinoma (STAD)." (PMID 36825202, 2023). "But, FDX1 mRNA expression was high only in GBM (glioblastoma multiforme) and STAD (stomach adenocarcinoma)." (PMID 37193786, 2023). "Consequently, our findings suggest that FDX1 may serve as a cancer immune checkpoint in glioblastoma." (PMID 38114959, 2023). "Our findings suggest that FDX1 acts as an upstream factor, regulating DNA-PKcs and modulating HIF-1α expression levels through distinct pathways in glioblastoma cells under severe hypoxia." (PMID 40244269, 2025). "In conclusion, we demonstrated that FDX1 knockdown suppresses cellular radioresistance under severe hypoxia by regulating ATM, DNA-PKcs, Akt, and EGFR expression in the human glioblastoma cell line T98G." (PMID 40244269, 2025). "Only GBM (Glioblastoma multiforme) and STAD (stomach adenocarcinoma) samples showed higher FDX1 expression than the corresponding normal samples." (PMID 36292610, 2022). "In order to predict the impact of FDX1 expression on chemotherapy, we utilized the pRRophetic algorithm to evaluate the response to chemotherapy based on the half-maximal inhibitory concentration (IC50) for patients with glioblastoma multiforme (GBM) in the GDSC database." (PMID 38114959, 2023). "Most copper induced cell death genes were downregulated in various cancers, such as FDX1 in cholangiocarcinoma (CHOL); LIAS and LIPT1 in bladder cancer (BLCA); PDHB in glioblastoma (GBM) and kidney chromophobe cancer (KICH)." (PMID 36581992, 2022).
liver cancer (13 papers, 2022 to 2025). An epithelial or non-epithelial malignant neoplasm that arises from the liver. "Recent studies have shown that high expression of ferredoxin 1 (FDX1), a cuproptosis-related genes, was associated with displayed higher immune cell infiltration and lower PD-L1, and decreased cell viability in liver cancer samples." (PMID 38200525, 2024). "FDX1 is a key regulator of cuproptosis, and the severity of liver cancer gradually increases, indicating that patients with a low expression of FDX1 have poorer OS than patients with a high expression of FDX1." (PMID 38200525, 2024). "Wang and colleagues recently observed that ferroptosis inducers, sorafenib and erastin, can enhance cuproptosis in primary liver cancer cells, mainly through upregulating FDX1 protein levels and promoting the aggregation of lipoylated proteins." (PMID 38918694, 2024). "To investigate the role of AL590705.3, LINC02870, KDM4A-AS1, and MKLN1-AS in liver cancer cells, we fistly detected the expression of FDX1 in HepG2, Hep3B, Huh-7, 97L, and 97H cells." (PMID 37056336, 2023). "The low expression of FDX1 in most tumors and the up-regulation of FDX1 in liver cancer, colon cancer, kidney cancer, and other bioinformatics analysis can mediate the good prognosis of tumor patients." (PMID 37318594, 2023). "There is a study based on ferredoxin 1 (FDX1), the key regulator of cuproptosis, and its related genes to establish a cuproptosis-related signature to evaluate the prognosis of liver cancer and guide treatment." (PMID 37291405, 2023). "The classic regulator of copper induced death FDX1 was investigated and was significantly reduced in renal cancer, liver cancer, gastric adenocarcinoma, and other cancers compared with the normal control." (PMID 36581992, 2022). "FDX1 had a relatively high expression in the liver among various normal tissues; however, its expression in liver cancers cannot be detected, suggesting a possible downregulation of the gene during the development of HCC." (PMID 35898502, 2022). "Furthermore, FDX1 knockdown stimulated the proliferation and migration of hepatic cancer cells by reducing cuproptosis." (PMID 38918694, 2024). "Moreover, we used the Kaplan–Meier plotter tool to analyze the overall survival of patients with liver cancer based on the expression of the FDX1, DBT, GCSH, SLC31A1, and DLAT genes." (PMID 37763758, 2023). "The high expression of FDX1 exhibited a longer survival than the low-expression group in TCGA-LIHC, GSE14520, and the liver cancer project (code: LIRI_JP) of the International Cancer Genome Consortium (ICGC) (ICGC-LIRI) cohorts." (PMID 37361595, 2023). "We further validated the expressions of the CRGs in liver cancer cell lines and related normal cells and found that the expression of DLAT and DLA are much higher and FDX1 lower in cancer cell lines compared to normal cells." (PMID 37608927, 2023).
polycystic ovary syndrome (11 papers, 2021 to 2025). A disorder that manifests as multiple cysts on the ovaries. "A study found that FDX1 can regulate the apoptosis and autophagy processes in cells associated with polycystic ovary syndrome." (PMID 41463095, 2025). "FDX1 is associated with the development of neonatal testis in mice and is involved in the development of polycystic ovary syndrome (PCOS) by regulating steroid metabolism and mitochondria in rat granulosa cells." (PMID 36210836, 2022). "In addition, FDX1 is involved in the development of polycystic ovary syndrome by regulating mitochondrial and steroid metabolism." (PMID 36173462, 2023). "FDX1 was related with steroid metabolism and mitochondrial and may participate in the development of polycystic ovary syndrome." (PMID 36915038, 2023). "Investigations on the relationship between FDX1 expression and diseases showed that downregulation of FDX1 was probably related to the onset of polycystic ovary syndrome (PCOS), while a certain FDX1 genotype was a potential risk factor for glomerulonephritis immunoglobulin A (IgA) nephropathy." (PMID 36605188, 2022). "They found that FDX1 was related to steroid metabolism in mitochondria and may be involved in developing polycystic ovary syndrome." (PMID 36105937, 2022). "In addition, recent studies have suggested that the FDX1 gene may play important roles in diseases such as lung adenocarcinoma and polycystic ovary syndrome (PCOS)." (PMID 35875087, 2022). "FDX1 can regulate glucose, lipid and amino acid metabolism, affect the prognosis of LUAD and may participate in the occurrence and development of polycystic ovary syndrome (PCOS)." (PMID 36755576, 2023).
cholangiocarcinoma (9 papers, 2022 to 2025). A carcinoma that arises from the intrahepatic biliary tree (intrahepatic cholangiocarcinoma) or from the junction, or adjacent to the junction, of the right and left hepatic ducts (hilar cholangiocarcinoma). "In cholangiocarcinoma (CCA), a 4-gene signature (ATP7A, FDX1, DBT, LIAS) was established as an independent prognostic factor, while another study constructed a signature model containing 10 genes." (PMID 41201667, 2025). "However, in a few tumors (bladder urothelial carcinoma (BLCA), cholangiocarcinoma (CHOL), mesothelioma (MESO) and rectum adenocarcinoma (READ), FDX1 expression was not correlated with genomic instability." (PMID 36226187, 2022).
osteosarcoma (9 papers, 2022 to 2025). A usually aggressive malignant bone-forming mesenchymal neoplasm, predominantly affecting adolescents and young adults. "FDX1 was found to be associated with the sensitivity of ifosfamide, which was one of the first-line chemotherapy agent in osteosarcoma." (PMID 37405988, 2023). "Our study found that FDX1 was associated with poor prognosis, suggesting FDX1 might participate in tumorigenesis and development of osteosarcoma." (PMID 37405988, 2023). "The hFOB 1.19 and MG‐63 cells were utilized to validate the mRNA expression of SQLE and FDX1 in osteosarcoma (OS)." (PMID 38546286, 2025). "In the osteosarcoma tissue, FDX1, TOMM20, and NDUFB9 are all overexpress to promote the development of osteosarcoma." (PMID 38800967, 2024). "According to some research, FDX1 was strongly expressed in osteosarcoma tissue, and patients who had high levels of FDX1 expression had a bad prognosis." (PMID 37405988, 2023). "The result provides a new reference for FDX1 in comprehensive treatment and chemotherapy resistance of osteosarcoma." (PMID 37405988, 2023). "The results of wound healing assay and transwell assay indicated that FDX1 promoted the migration of osteosarcoma cells." (PMID 37405988, 2023). "A total of six cuproptosis-mitochondrion genes (FDX1, COX11, MFN2, TOMM20, NDUFB9 and ATP6V1E1) were identified to be associated with the prognosis of osteosarcoma." (PMID 37405988, 2023). "In this study, a total of six key cuproptosis-mitochondrion genes (FDX1, TOMM20, NDUFB9, COX11, MFN2 and ATP6V1E1) associated with prognosis of osteosarcoma were finally identified." (PMID 37405988, 2023). "Among them, FDX1, TOMM20 and NDUFB9 were associated with poor survival of osteosarcoma while COX11, MFN2 and ATP6V1E1 predicted good." (PMID 37405988, 2023). "Compared with hFOB1.19, western blotting revealed that the expression of FDX1 was significantly elevated in osteosarcoma cells." (PMID 37405988, 2023). "And we explored the function of FDX1 in osteosarcoma by western blotting, CCK8, colony formation assay, wound healing assay and transwell assays." (PMID 37405988, 2023). "We conducted some functional experiments and found that FDX1 mainly involves the migration of osteosarcoma and didn’t affect the proliferation of osteosarcoma." (PMID 37405988, 2023). "The Western blotting results showed that compared to the normal osteoblast hFOB1.19, the protein expression level of FDX1 was significantly increased in osteosarcoma cell lines, with the most significant increase observed in MG63 cells." (PMID 37405988, 2023). "Second, we have explained the function of cuproptosis hub gene FDX1 in osteosarcoma: FDX1 mainly promotes the migration of osteosarcoma rather than proliferation." (PMID 37405988, 2023). "in addition, the protein expression level of LIPT1 was significantly elevated in both 143B and U2OS, and the protein expression level of FDX1 was significantly overexpressed in three osteosarcoma cell lines HOS, 143B, and U2OS." (PMID 35967366, 2022). "The prognosis of patients with osteosarcoma may also be impacted by the high expression of FDX1 through a variety of mechanisms." (PMID 37405988, 2023). "Therefore, we speculate that the high expression of FDX1 may aggravate the malignancy of osteosarcoma by promoting the migration of osteosarcoma cells." (PMID 37405988, 2023). "It suggested that inhibition of FDX1 might be a viable therapeutic option for osteosarcoma." (PMID 37405988, 2023). "Together, these mechanisms may be involved in the prognostic impact of FDX1 on osteosarcoma." (PMID 37405988, 2023). "The expression of FDX1, COX11, MFN2, TOMM20 and NDUFB9 at mRNA level was elevated in osteosarcoma cells compared with normal osteoblast hFOB1.19." (PMID 37405988, 2023). "Expression of cuproptosis-related genes was closely related in osteosarcoma, and GALNT14 expression was significantly positively correlated with FDX1, a key regulator of cuproptosis." (PMID 38024474, 2023).
osteosarcoma (continued). "PCR analysis showed increased mRNA levels of the genes FDX1 and SQLE in osteosarcoma tissues." (PMID 38546286, 2025). "Finally, it was experimentally verified that the expression of FDX1, COX11, MFN2, TOMM20 and NDUFB9 at mRNA levels was elevated in osteosarcoma." (PMID 37405988, 2023). "We have only conducted functional experimental studies on FDX1 in relation to a prognostic model, while the roles of the other five genes in osteosarcoma have not been thoroughly analyzed." (PMID 37405988, 2023). "Functional experiments indicated that FDX1 mainly promoted the migration of osteosarcoma rather than proliferation." (PMID 37405988, 2023). "colony formation assay and CCK-8 assay revealed that overexpression of FDX1 did not affect the viability of osteosarcoma cells." (PMID 37405988, 2023). "We conducted a series of in vitro experiments and found that FDX1 mainly promoted the migration of osteosarcoma rather than proliferation." (PMID 37405988, 2023). "Furthermore, there are no literature findings on FDX1 migration and proliferation in osteosarcoma." (PMID 37405988, 2023). "However, we are not aware of any study on the immunological aspects of FDX1, TOMM20, NDUFB9, COX11, MFN2 and ATP6V1E1 in osteosarcoma for the time being, which is a direction we need to study subsequently." (PMID 37405988, 2023).
colorectal cancer (8 papers, 2022 to 2025). A primary or metastatic malignant neoplasm that affects the colon or rectum. "Abnormal FDX1 expression has been associated with colorectal cancer and can affect cellular energy metabolism and redox balance." (PMID 38898987, 2024). "Next, we used HCT116 human colorectal cancer cells to determine if the effect of FDX1 on lipid metabolism observed in murine cells is conserved in human cells." (PMID 38251655, 2024). "The study revealed that, compared to normal tissues, genes FDX1, DLD, DBT, DLST, and DLAT were significantly downregulated in colorectal cancer tissues, while LIPT1, GCSH, and ATP7B genes were upregulated." (PMID 40276654, 2025). "It was found that the mutation frequency of each regulator is relatively low, of which ATP7A showed the highest mutation rate, followed by ATP7B and LIPT1, while FDX1, CDKN2A, SLC31A1, and GCSH showed no mutation in all colorectal cancer tissues." (PMID 36248908, 2022).